CD163 (CD163 molecule)
Diseases named in the same sentence as CD163 in open-access papers (continued):
Sharing a sentence is not in itself a finding about the gene and the disease.
rectal cancer (8 papers, 2013 to 2022). A primary or metastatic malignant neoplasm that affects the rectum. "For example, CD163 expression on rectal cancer cells is associated with early local recurrence and reduced survival time." (PMID 26267609, 2015). "In summary, we have identified biological valid differences in the distribution of CCR2 and CD163 expression among colon and rectal cancer patients." (PMID 36733385, 2022). "Here we have identified biological valid differences in the distribution of CCR2 and CD163 expression on monocytes among colon and rectal cancer patients." (PMID 36733385, 2022). "In rectal cancer patients, CD163 expression in tumor cells was found in 17% of primary tumors from patients not treated with preoperative irradiation compared with 31% of those given preoperative radiotherapy (p < 0.044)." (PMID 28881654, 2017). "The subsets of CD163+ monocytes were indicative for chemotherapy impact in rectal cancer patients." (PMID 36733385, 2022). "The major finding is both NAC and surgical intervention affect proportion of CCR2+ and CD163+ monocytes within non-classical CD14-CD16+ and CD14+CD16+ subsets in patients with CRC, and the effects are specific for colon and rectal cancer patients." (PMID 36733385, 2022). "Both NAC and surgical intervention affected proportion of CCR2+ and CD163+ monocytes within non-classical CD14-CD16+ and CD14+CD16+ subsets in patients with CRC, and effects were specific for colon and rectal cancer patients." (PMID 36733385, 2022).
type 1 diabetes (8 papers, 2012 to 2025). "A previous study has shown that sCD163 is higher in male adults with type 1 diabetes compared to healthy controls and that tumour necrosis factor-like weak (TWEAK), inducer of apoptosis) and ligand to membrane-bound CD163, is associated with complications." (PMID 36404844, 2022). "We also found that the down-regulated pathways affected by CD163 included antigen processing and presentation, autoimmune thyroid disease, graft versus host disease, and intestinal pathways immune network for IGA production and type I diabetes mellitus." (PMID 40599778, 2025). "CD163, MCEMP1 and RETN may jointly regulate complement and coagulation cascades, toll like receptor signaling pathway, graft versus host disease, type I diabetes mellitus." (PMID 40599778, 2025). "Using machine learning models to predict the potential mechanisms and targets of CD163, MCEMP1, and RETN proteins, CD163, MCEMP1 and RETN may jointly regulate complement and coagulation cascades, toll like receptor signaling pathway, graft versus host disease, type I diabetes mellitus." (PMID 40599778, 2025).
Autoimmunity (7 papers, 2013 to 2025). The occurrence of an immune reaction against the organism's own cells or tissues. "CD163, a scavenger receptor expressed on macrophages, has been identified as a marker of monocyte and macrophage activation, and its soluble form has been linked to inflammation in various autoimmune conditions." (PMID 39767148, 2024). "Additionally, CD163 and MCP-1 in the inflammatory lesions and the fold change upon ICI treatment in expression levels on monocytes in blood tended to be associated with ICI-induced autoimmune conditions." (PMID 39982537, 2025). "Alternatively, excess ectodomain shedding of MerTK and CD163 by ADAM-17 may account for a functional impairment of M2c monocytes/macrophages and could itself contribute to chronic inflammation, defective clearance of early ACs and autoimmunity." (PMID 24325951, 2013).
Cerebral ischemia (7 papers, 2012 to 2024). Restriction of arterial blood supply to the brain associated with insufficient oxygenation to support the metabolic requirements of the tissue. "Additionally, a functional analysis of the genes overexpressed in CD163+ CNS border-associated macrophages after brain ischemia has been reported in rats, supporting the activation of neovascularization processes and of the hypoxia-inducible factor-1 pathway in the acute phase." (PMID 34201498, 2021). "Our study suggests that CD163+ macrophages attract granulocytes to the leptomeningeal and perivascular spaces in response to brain ischemia." (PMID 30092836, 2018). "Altogether, these results suggested the possibility that CD163+ macrophages participated in the recruitment of leukocytes after brain ischemia." (PMID 30092836, 2018). "Functional analysis of genes over-represented in CD163+ BAMs after brain ischemia versus controls highlighted the activation of neovascularization processes and the HIF-1 pathway." (PMID 30092836, 2018). "In this study, we investigated the phenotype and function of CD163+ BAMs in the acute phase of cerebral ischemia/reperfusion in rats." (PMID 30092836, 2018). "Potential therapeutic options to prevent delayed cerebral ischemia ought to concentrate on augmenting the capacity of the intrathecal CD163-haptoglobin–hemoglobin scavenging system and strategies to encourage hemoglobin efflux from the brain." (PMID 22380637, 2012). "We then checked that CD163+ cell depletion was maintained after brain ischemia." (PMID 30092836, 2018). "In contrast to inflammatory or ischaemic diseases of the brain, acute sepsis does not present with the expression of the anti-inflammatory microglia markers CD163 or CD206." (PMID 35295600, 2022). "In contrast to inflammatory or ischaemic diseases of the brain, the anti‐inflammatory microglia markers CD163 or CD206 were not expressed in acute sepsis." (PMID 29804289, 2019).
clear cell renal cell carcinoma (7 papers, 2015 to 2026). "Supporting our data, increased infiltration of CD163+ TAMs in immTLS was observed by IHC in specimens of clear cell renal cell carcinoma and metastatic gastric cancer." (PMID 41429763, 2025).
diabetic nephropathy (7 papers, 2017 to 2025). "Notably, CD163 is a classical marker of alternatively activated (M2) macrophages, which have been shown to mediate anti-inflammatory responses and tissue repair in diabetic nephropathy." (PMID 40969366, 2025). "In conclusion, our study identifies COL1A2, CD163, FN1, and CCL2 as key molecular players involved in fibrosis, immune activation, and inflammatory signaling in diabetic nephropathy." (PMID 40969366, 2025). "Our study identifies COL1A2, CD163, FN1, and CCL2 as key molecular signatures involved in the immunoinflammatory and fibrotic progression of diabetic nephropathy." (PMID 40969366, 2025).
epithelial dysplasia (7 papers, 2015 to 2025). "A high CD163+ MΦ number showed significantly positive associations with the degrees of epithelial dysplasia, abnormal Ki‐67 expression and cytokeratin 13 (CK13) loss in TL tissues." (PMID 31890299, 2019). "On the other hand, in low-grade epithelial dysplasia, CD163-positive cells with a round shape increase around the epithelial tissue, and in high-grade epithelial dysplasia, CD163-positive cells with a dendritic form cluster more around the epithelial tissue." (PMID 40940867, 2025). "In summary, our current study highlighted the contributing role of β-catenin signaling and CD163 + of M2 macrophages in the progression of epithelial dysplasia in cases of OPMDs." (PMID 39327577, 2024). "However, in moderate epithelial dysplasia, CD163-positive macrophages become more prominent, particularly in periepithelial regions." (PMID 40940867, 2025). "In addition, several investigators have reported about the correlation between CD163+ macrophages and epithelial dysplasia and the malignancy of oral precancerous lesions." (PMID 32075061, 2020). "ZSP-M inhibited the degree of epithelial dysplasia in precancerous lesions by inhibiting the expression of the TNFAIP6 and CD163 proteins in the precancerous lesions of the tongue." (PMID 39068492, 2024). "An increase in the rate of CD163+ TAM infiltration was observed in mild and moderate epithelial dysplasia, which positively correlated with the rate of intraepithelial CD4+ Th cell infiltration." (PMID 26242181, 2015). "Another important study showed a significant elevation in density of CD163 + M2 macrophages in OPMD cases with moderate epithelial dysplasia compared to cases without epithelial dysplasia." (PMID 39327577, 2024). "The results of our analyses demonstrated that the number of infiltrating CD163+ MΦs but not the numbers of CD206+ MΦs and CD204+ MΦs had significantly positive correlations with the degrees of epithelial dysplasia, abnormal Ki‐67 expression, and CK13 loss in TL tissues." (PMID 31890299, 2019).
histiocytic sarcoma (7 papers, 2012 to 2026). An aggressive malignant neoplasm with a poor response to therapy, usually presenting as stage III/IV disease. "We also elucidate the role of the CD163 biomarker in diagnosing HS and using surgery and adjuvant radiotherapy (RT) as a successful treatment approach for primary CNS histiocytic sarcoma." (PMID 35663678, 2022). "In immunohistochemistry, these atypical cells were specifically positive for CD68 (KP-1), CD163, and lysozyme, which was consistent with histiocytic sarcoma (HS) of the spleen." (PMID 23075171, 2012). "Immunohistochemistry tests confirmed the cells were of histiocytic origin, strongly expressing CD68, CD163, LCA, and S100, confirming the diagnosis of histiocytic sarcoma." (PMID 42256916, 2026). "Histiocytic sarcoma (HS) is an uncommon malignant neoplasm arising from mature histiocytes and most commonly characterized by the immunophenotypic expression of CD68, CD163, or lysozyme." (PMID 31687231, 2019). "Histiocytic sarcoma (HS) is an extremely rare hematopoietic neoplasm that originates from the macrophage lineage and shows a sarcoma‐like spread of CD4+, CD68+, PU.1+, and CD163+ histiocytic cells." (PMID 40938275, 2025). "Still, immunohistochemistry of histiocytic sarcoma shows the expressions of histiocytic markers, including CD68, CD163 and lysozyme, with the absence of B‐cell, T‐cell, dendritic cell, epithelioid cell, myeloid cell markers." (PMID 38450981, 2024).
leprosy (7 papers, 2016 to 2025). Leprosy is a chronic infectious disease affecting primarily the skin and peripheral nervous system. "CD14+CD209+CD163+ triple positive cells are also described in the human dermis, in a murine leprosy model, and in the decidua of early human pregnancy." (PMID 36291154, 2022). "Leprosy household contacts had decreased soluble CD163 and heme oxygenase 1 (HO-1) serum levels when compared with healthy donors and leprosy patients." (PMID 35552484, 2022). "In leprosy, a similar relationship has previously been suggested by the observation in lesion biopsies of macrophages expressing CD163 that are heavily infected with M. leprae." (PMID 28355218, 2017). "Linear regression analysis indicates that CD163 and OAS1 expression are coordinately expressed (P = 0.0004, R2 = 0.6019) and two way ANOVA analysis confirms that leprosy type of the lesion is significantly (P = 0.0003) associated with differential gene expression of CYP27B1, CD163 and OAS1." (PMID 30300363, 2018). "In parallel, the gene expression profiles of the 50 common genes were examined in leprosy lesions, with the premise that inverse correlation with CD163 expression may indicate a role in regulating M1 MΦ differentiation at the site of disease." (PMID 27532668, 2016). "By contrast, in the progressive, lepromatous (L-lep) form of leprosy, patient lesions are characterized by disorganized granulomas containing MΦ which co-express CD209 and CD163 but lack antimicrobial activity." (PMID 27532668, 2016). "Toll-like receptors (TLR) 1, TLR2, TLR4, dendritic cell-specific intercellular adhesion molecule-3-grabbing non-integrin (DC-SIGN), and CD163 mediate the interaction between macrophages and M. leprae in leprosy, which increases IL-6 and IL-10 secretion." (PMID 41239264, 2025). "In the self-limited, tuberculoid (T-lep) form of leprosy, disease lesions contain well-organized granulomas with M1 MΦ, expressing the MΦ marker CD209, but negative for the haptoglobin receptor CD163, yet armed with antimicrobial effector function." (PMID 27532668, 2016).
liver cancer (7 papers, 2013 to 2025). An epithelial or non-epithelial malignant neoplasm that arises from the liver. "CD163 showed a significant association with worse OS in cancer patients, except for lung and liver cancer patients." (PMID 33828973, 2021). "We detected the expression of CYPJ, CD86 (a marker for M1 TAMs), CD163 (a marker for M2 TAMs), CD8 (a marker for CD8+ T cell), and EpCAM (a marker for tumor cells) in tissues from liver cancer patients using the mIHC method." (PMID 40520002, 2025). "In this study, we have found that lncRNA‐CRNDE can promote the M2 polarization of macrophages through the high expression of CD163 to further promote tumour angiogenesis, which is one of the mechanisms by which CRNDE promotes liver cancer progression." (PMID 33742511, 2021). "And the marker CD163 itself could not be used as an indicator for the determination of the subpopulation of M2-macrophages in liver and in liver cancer tissue." (PMID 23555776, 2013).
neuroblastoma (7 papers, 2015 to 2024). Neuroblastoma (NB) is the most common solid, extracranial childhood tumor. "The 3D correlation analysis indicated that high-risk neuroblastomas co-expressed PD-L1, PD-1, and CD163 (an M2 TAM marker), suggesting the presence of M2-like TAMs with the PD-L1+PD-1+ phenotype." (PMID 35525858, 2022). "In multiple datasets of neuroblastoma patients, gene expression of CD73 correlated strongly with myeloid cell markers CD163 and CSF-1R in neuroblastoma tumors, and associated with worse survival in high-risk patients." (PMID 28123870, 2016). "Indeed, our data suggest that CD163+ macrophages could function as anti-tumor phagocytes in high-risk neuroblastoma at diagnosis." (PMID 35525858, 2022). "In addition, most macrophages co-expressing high levels of CD68 and CD163 could function as anti-tumor phagocytes in high-risk neuroblastomas at diagnosis." (PMID 35525858, 2022). "The immunofluorescence staining results indicated a significant reduction in the expression levels of CD163 in macrophages co-cultured with HK3-knockdown neuroblastoma cell lines, compared to the control group." (PMID 38714539, 2024). "IHC staining of high-risk neuroblastoma tissues with anti-CD68 and anti-CD163 antibodies revealed that a number of macrophages positive for these markers were present in a similar density and distribution pattern." (PMID 35525858, 2022). "Survival analysis further showed that high-risk neuroblastoma patients from Cohort 1 having tumors with both high CD68 and CD163 expression exhibited better survival." (PMID 35525858, 2022). "Our results suggest that there are CD163+ M2-like TAMs co-expressing PD-L1 and PD-1 in the TME of high-risk neuroblastomas." (PMID 35525858, 2022). "Chromosome 11q deletion or MYCN amplification in neuroblastomas exhibit higher numbers of M2-polarized (CD163+) macrophages and an activated Th2-lymphocytes/M2-macrophage axis compared to neuroblastoma lacking these mutations." (PMID 38087370, 2023). "In vitro, neuroblastoma-exposed monocytes/macrophages upregulated M2 markers (CD163, CD204, IL-10)." (PMID 38087370, 2023). "Moreover, IHC staining of serial sections from an unfavorable histology MYCN amplified neuroblastoma demonstrated that the majority of CD68+ macrophages co-expressed CD163." (PMID 35525858, 2022). "We detected the significantly correlated expression of M2 TAMs marker genes (CD163, CD204, CD206) and M-MDSC marker genes (CD11B, CD14, CD33) in the high-risk neuroblastoma examined, suggesting that the various numbers of M2 TAMs and MDSCs are present in the high-risk neuroblastoma TME." (PMID 33968044, 2021). "Interestingly, in two neuroblastoma patient cohorts, the presence of TAMs expressing PD-L1, as well as the expression of the SLAMF7 pathway and CD163 in TAMs, was found to be beneficial for high-risk patients and correlated with improved survival following immunotherapy." (PMID 38087370, 2023). "Western blot analyses revealed a reduction in CD163 and CD206 expression in macrophages co-cultured with sh-HK3 neuroblastoma cells." (PMID 38714539, 2024).
parasitemia (7 papers, 2018 to 2025). "CD163 is used as a molecular marker associated with parasitemia, and its expression is directly associated with increased parasitemia in infected individuals." (PMID 39859202, 2025). "Both cellular subpopulations also highly expressed CD163 on D5 in the spleen, which is when parasitemia increases." (PMID 36310859, 2022). "Immunohistochemistry for eight antibodies (CK19, CD3, Foxp3, CD20, Iba1, CD68, CD163, and CD204) was conducted to analyze the pathology of these parasitic infections." (PMID 32714946, 2020). "Macrophages and lymphocyte subsets expressing CD163 or WC1, respectively, play a role against certain parasite infections (e.g. Theileria parva, Leishmania braziliensis, Trypanosoma vivax, or Neospora caninum), but no direct interaction with parasite helminth structures has been previously reported." (PMID 30500820, 2018).
serous ovarian cancer (7 papers, 2016 to 2022). "As for serous carcinoma, total CD68+ macrophage infiltration together with CD163 expression was significantly increased in high-grade serous ovarian cancer (HGSOC) compared to low-grade serous ovarian cancer (LGSOC)." (PMID 33194645, 2020). "In keeping with these literature data, we found a strong association between intra-tumor TAM density and microvessel density, so that CD31 expression closely paralleled density of tumor-infiltrating CD163+ macrophage in low and high-grade serous ovarian cancer." (PMID 27462782, 2016).
cholangiocarcinoma (6 papers, 2018 to 2025). A carcinoma that arises from the intrahepatic biliary tree (intrahepatic cholangiocarcinoma) or from the junction, or adjacent to the junction, of the right and left hepatic ducts (hilar cholangiocarcinoma). "Immunohistochemistry results from 38 patients also showed that the level of CD163+ macrophage in cholangiocarcinoma tissues was associated with a poor differentiation of tumor cells and tumor metastasis." (PMID 30469416, 2018). "Interestingly, patients with cholangiocarcinoma whose serum IgG1-G0F ≥40% had more CD163+ tumor-associated macrophages in cancerous tissues than adjacent non-cancerous counterparts." (PMID 30469416, 2018). "The expression of TRIM47 and CD163 in the cholangiocarcinoma patient samples from The Cancer Genome Atlas database was positively correlated." (PMID 41380966, 2025). "We found that macrophages stimulated with the supernatant of cholangiocarcinoma cells expressed high levels of M2 markers, including CD163, CD206, ARG-1, and IL-10." (PMID 39256888, 2024). "High densities of CD163+ macrophages were correlated with the occurrence of extrahepatic metastases in cholangiocarcinoma, possibly through the activation of signalling pathways involved in epithelial-to-mesenchymal transition." (PMID 36068277, 2022). "Both IgG1-G0F and CD163+ macrophage in tumor foci were shown to link to an early cholangiocarcinoma recurrence in a univariate but not a multivariate Cox regression model, suggesting that these two factors were tightly correlated." (PMID 30469416, 2018).
colon adenocarcinoma (6 papers, 2019 to 2025). "In this study, we found that knockout of PRDX1 robustly suppressed AOM/DSS‐induced colonic adenocarcinoma compared with wild‐type C57BL/6J mice, accompanied by highly infiltrated CD4+/CD8+ T cells and reduced CD163+ tumor‐associated macrophages (TAMs)." (PMID 41306557, 2025). "IF‐based double staining experiments using colon adenocarcinoma tissues confirmed that AKR1B1 was indeed expressed by CD163 positive M2 macrophages." (PMID 40396420, 2025). "In colon adenocarcinoma, most of the CD163 positive cells were also positively stained with AKR1B1." (PMID 40396420, 2025).